IRF7 (interferon regulatory factor 7)
Diseases named in the same sentence as IRF7 in open-access papers (continued):
Sharing a sentence is not in itself a finding about the gene and the disease.
ovarian carcinoma (5 papers, 2014 to 2025). A malignant neoplasm originating from the surface ovarian epithelium. "Moreover, patients with high TNFSF10 expression usually exhibited a good response to chemotherapy, while TNFRSF4 was associated with chemosensitivity and good prognosis in ovarian cancer patients, and IRF7 was upregulated in patients in the chemotherapy responsive group." (PMID 36590751, 2022). "In ovarian cancer cell lines SKOV3 and A2780, CS knockdown increased the mRNA levels of ISG15, IRF7, CASP7, and DDX58, according to microarray and qPCR studies." (PMID 41515967, 2025). "Treatment of the ovarian cancer cell line A2780, for 72 hours with 500 nM carboplatin does not lead to overexpression of AIM genes IFI27, IRF7, IL15, or MAGEB2, all of which are increased in AZA-treated cells." (PMID 24583822, 2014).
Stroke (5 papers, 2011 to 2025). Sudden impairment of blood flow to a part of the brain due to occlusion or rupture of an artery to the brain. "For example, ASO-based drugs have already shown clinical success in other neurological and cardiovascular conditions, suggesting that RNA-based therapeutics could provide feasible intervention strategies for modulating GATA2/IRF7-driven gene networks in stroke." (PMID 40963808, 2025). "The differences in the concentrations of interferon regulatory factor 7 (IRF7) and thymidine phosphorylase TYMP-4 persisted for the next three days from the onset of stroke (a significant difference between group B and the control)." (PMID 35268287, 2022). "This possibility is supported by our scRNA-seq data showing significant upregulation of interferon regulatory factor 7 (IRF7) in MG from aged brain following stroke, whereas other IRFs were not markedly changed (data not shown)." (PMID 36824976, 2023).
acute pyelonephritis (4 papers, 2019 to 2025). "IRF-7 controls inflammation and renal tissue damage in the murine acute pyelonephritis model, through a network of pathology-associated genes." (PMID 31181116, 2019). "Indeed, IRF7 promoter polymorphisms with lower IRF7 expression were found to be protective against recurrent acute pyelonephritis in children." (PMID 35860746, 2022). "In acute pyelonephritis, IRF3 is required for mucosal innate immunity and protects the kidney from uropathogenic E. coli, whereas IRF7 agonism triggers a hyperinflammatory response and increases kidney injury." (PMID 41212050, 2025).
acute respiratory distress syndrome (4 papers, 2016 to 2024). Progressive and life-threatening pulmonary distress in the absence of an underlying pulmonary condition, usually following major trauma or surgery. "In humans, homozygous IRF7 deficiency was shown to be associated with severe influenza A virus infection and acute respiratory distress syndrome." (PMID 34389779, 2021).
bronchiolitis (4 papers, 2017 to 2022). Inflammation of the bronchioles characterized by swelling of the bronchioles and mucus accumulation. "As occurs clinically, the severe bronchiolitis that developed in IRF7-/- neonatal mice was associated with greater neutrophilic inflammation, tissue oedema, and pronounced sloughing of the airway epithelium." (PMID 32658914, 2020). "Additionally, we identified that IRF7-/- mice that had experienced severe bronchiolitis in infancy were predisposed to develop experimental allergic asthma in later life following exposure to low-dose cockroach allergen extract (CRE)." (PMID 32658914, 2020).
gastric cancer (4 papers, 2022 to 2024). A primary or metastatic malignant neoplasm involving the stomach. "The present study have unveiled the tumor-suppressive role of circ0007360 in gastric cancer progression and have uncovered the modulation of the miR-762/IRF7 axis as the underlying mechanism." (PMID 35252169, 2022). "In our study, through loss-of-function experiments, we find that IRF7 acts as a suppressor of the survival, migration, and invasion of gastric cancer cells." (PMID 35252169, 2022). "The circ0007360/miR-762/IRF7 axis inhibited the survival, migration and invasion of gastric cancer cells and slowed down the progression of gastric cancer." (PMID 37251373, 2023). "Another study on different gastric cancer cell lines revealed that the activation of circ0007360/miR-762/IRF7 axis suppressed the survival, migration and invasion of gastric cancer cells, indicating the inhibitory role of IRF7 in gastric cancer." (PMID 37251373, 2023). "More importantly, we have shown that IRF7 is a negative regulator of stemness in gastric cancer cells." (PMID 35252169, 2022). "Since we validated that IRF7 is a downstream target gene of miR-762, the following investigations were performed to confirm the significance of IRF7 in miR-762-induced gastric cancer progression." (PMID 35252169, 2022). "In summary, our results revealed that activation of the circ0007360/miR-762/IRF7 axis is a novel mechanism for the attenuation of gastric cancer progression." (PMID 35252169, 2022). "Moreover, RT-qPCR results confirmed that miR-762 levels were enhanced, while IRF7 levels were reduced, upon depletion of circ0007360 in the isolated tumors formed by the human gastric cancer cells." (PMID 35252169, 2022). "This may be further complemented by ectopic expression analysis to better understand the effects of IRF7 on gastric cancer progression." (PMID 35252169, 2022). "Moreover, NCAPD3 loss activates IRF7 and DDIT3 to regulate apoptosis in gastric cancer cells." (PMID 38711992, 2024). "Moreover, taking all these in vitro data together, we indicate that the progression of gastric cancer may be attenuated by the circ0007360/miR-762/IRF7 axis." (PMID 35252169, 2022). "Our analysis indicated that PARP1 expression was negatively correlated with the expression of ISGs (IRF7 and ISG15) in human stomach cancer (n = 407 samples, P < 0.01), which is consistent with our in vitro study observations." (PMID 36624848, 2022). "Furthermore, we demonstrated that interferon regulatory factor 7 (IRF7), which was validated as a target gene of miR-762, serves as an indirect target of circ0007360 to attenuate the progression of gastric cancer." (PMID 35252169, 2022). "Although the promoter of IRF7 was hypermethylated in gastric cancer samples, the effect of IRF7 on gastric cancer progression has not been reported." (PMID 35252169, 2022). "Therefore, NCAPD3 knockdown may activate IRF7, DDIT3, and HBEGF expression to promote gastric cancer cell apoptosis." (PMID 38711992, 2024).
glioblastoma (4 papers, 2023 to 2024). The most malignant astrocytic tumor (WHO grade IV). "Spatial localization and metabolism of the IRF7 regulon and IRF7 were verified in situ using six cases of spatial transcriptome sequencing: IDH wild‐type glioblastoma, glioblastoma cell tumors with secondary surgery, and paraneoplastic tissues." (PMID 39492838, 2024). "Finally, in IDH wild‐type glioblastomas, metabolic signaling pathways of cell subpopulations with high IRF7 regulon expression, including tyrosine metabolism, purine metabolism, pentose phosphate pathway, cysteine, and methionine metabolism, were observed." (PMID 39492838, 2024). "In secondary glioblastomas, the IRF7 regulon expression was less distributed." (PMID 39492838, 2024). "In glioblastoma tumor tissues, IRF7 regulon expression was located at the tumor margin." (PMID 39492838, 2024). "We investigated the role of the IFN‐related gene IRF7 in IDH wild‐type and mutant glioblastomas using transcriptome sequencing analysis." (PMID 39492838, 2024). "Meanwhile, IRF7 mediates STAT3 expression and promotes the survival and stem cell differentiation potential of glioblastoma multiforme (GBM) cells through the IL-6-STAT3 signaling pathway, and then enhances the progression and invasion of GBM." (PMID 37251373, 2023).
H1N1 virus infection (4 papers, 2011 to 2022). "Endogenous Co-IP experiments further verified that NS2 associates with IRF7 following H1N1 virus infection." (PMID 36366509, 2022). "Following H1N1 virus infection, endogenous Co-IP experiment verified that NS2 was associated with IRF7 in the infected cells, with TBK1 as a positive control to interact with IRF7." (PMID 36366509, 2022). "For H1N1 influenza, 2 DNBs (IRF7, POLR1C) are also observed in the cytosolic DNA-sensing pathway." (PMID 28835768, 2017).
heart failure (4 papers, 2018 to 2025). Inability of the heart to pump blood at an adequate rate to meet tissue metabolic requirements. "Transcript levels of several established biomarkers, including Spp1, Sfrp1, Sfrp2, Tnc, Vim, Mmp9, and Tnfrsf1a, and several inflammatory markers that are known to be activated in heart failure, such as Cd44, Cd83, Ccl7, Irf7, and Nr4a2, were upregulated in the Myh6-McmTamDspfl/fl cardiomyocytes." (PMID 40608429, 2025).
Hepatitis C (4 papers, 2019 to 2024). "In a study of hepatitis C virus infection, Irf7 was found to inhibit hepatic inflammation by suppressing the production of proinflammatory cytokines." (PMID 37946128, 2023).
herpes simplex encephalitis (4 papers, 2016 to 2023). Herpes simplex virus encephalitis (HSE) is caused by the infection of the central nervous system by Herpes simplex virus (HSV) that could have a devastating clinical course and a potentially fatal outcome particularly with delay or lack of treatment. "In this study, we identified 2 genetic variants in IRF7 and UNC93B1 in our proband, who had full recovery from neonatal SEM disease but had a recurrence of HSV encephalitis during infancy after stopping preventative acyclovir therapy." (PMID 37097753, 2023). "Homozygous mutation in IRF7 led to a near-fatal infection by influenza virus, while mutations in TLR3 and in several other T1IFN-related genes markedly increase the risk of herpes simplex encephalitis (HSE)." (PMID 27580079, 2016).
Insulin resistance (4 papers, 2015 to 2025). Increased resistance towards insulin, that is, diminished effectiveness of insulin in reducing blood glucose levels. "Studies using mice with the deletion of IRF7 expression indicated that IRF7 promotes weight gain, hepatic fat deposition, and insulin resistance in the setting of HFD." (PMID 32660130, 2020). "Studies have shown that IRF-7 deficiency prevents DIO and insulin resistance in mice, and that IRF-7 expression is upregulated in the arteries of obese rats." (PMID 28660492, 2017).
liver fibrosis (4 papers, 2017 to 2025). "In this study, IFNα, IFNβ, ISG15, USP18, IFN-induced protein 44 (Ifi44), interferon-induced protein with tetratricopeptide repeat (Ifit) 1, Ifit2, IRF3, and IRF7 were significantly elevated in the CCl4-induced liver fibrosis model." (PMID 40260261, 2025). "Our results clearly revealed a failure to upregulate STAT2 and IRF7 in HCV/CMV co-infected patients with high grades of liver fibrosis when compared to HCV mono-infected patients." (PMID 28871140, 2017). "Because CXXC5 deficiency leads to IRF7 up-regulation in mice, which may potentially trigger a pro-fibrogenic response, it would be of great help to examine the phenotype of the CXXC5-null mice in the settings of the liver fibrosis." (PMID 34621736, 2021).
malaria (4 papers, 2012 to 2022). Malaria is a serious and sometimes fatal disease caused by a parasite that commonly infects a certain type of mosquito which feeds on humans. "Activation of TLR9 by A-type CpG DNA leads to induction of IFNA in pDCs through a MYD88- and IRF7-dependent mechanism, and previous work similarly found TLR9-dependence of IFNA production in pDCs during in vitro infection with malaria parasites." (PMID 23144737, 2012).
myeloma (4 papers, 2018 to 2025). "Further experimental validation confirmed that knocking down the expression of STING or IRF7 in myeloma cells significantly suppressed the expression of STING and PD‐L1 induced by melphalan or bortezomib." (PMID 40135791, 2025). "IRF7 was a significant immune-related gene, and myeloma patients used its expression level as a prognostic indicator to help guide their individualized treatment." (PMID 40406148, 2025). "Subsequent experimental validation corroborated that downregulating the expression of STING or IRF7 in myeloma cells markedly attenuates the induction of SEI1 by melphalan or bortezomib, and downregulation of SEI1 reduced the induction of PD‐L1 by melphalan or bortezomib." (PMID 40135791, 2025). "Next, we further analyzed the regulatory activity of TOP5 TF of C0 IGLC3+ Myeloma cells, and we visualized the expression of KLF6, NR3C1, IRF7, YY1 and JUN in all cells and different tissue sources." (PMID 40406148, 2025). "We analyzed the regulatory activity of TOP5 TFs in C0 IGLC3+ Myeloma cells and found that KLF6 was actively regulated in MM, and IRF7 and NR3C1 might be active in MM." (PMID 40406148, 2025). "The results showed that KLF6, NR3C1, IRF7 and YY1 were all actively regulated in C0 IGLC3+ Myeloma Cells, C1 IGHA1+ Myeloma Cells, and JUN was actively regulated in C0 IGLC3+Myeloma Cells, C1 IGHA1+ Myeloma Cells and C3 IGHG4+ Myeloma Cells." (PMID 40406148, 2025). "Additionally, we inoculated Irf7−/− mice with JEV-Nakayama (GIII), boosted with JEV-Bennett (GII), and administered a final intravenous boost with JEV-Nakayama before splenocyte-myeloma cell fusion." (PMID 29487230, 2018).
AIDS (3 papers, 2013 to 2023). A syndrome resulting from the acquired deficiency of cellular immunity caused by the human immunodeficiency virus (HIV). "Therefore, the simultaneous decrease of Th2 activity and the simultaneous increase of Th1 activity in the PFC suggests that IRF7 and its associated molecules may slow or prevent the development of AIDS in HIV-positive individuals." (PMID 36827648, 2023). "Species-specific differences in single amino acids within IRF7 were thought to be responsible for the lack of progression to AIDS during SIV infection of sooty mangabeys, although this observation was not supported by subsequent reports." (PMID 31830058, 2019). "Based on these results we concluded that IFN-α and IRF7 signaling in SMs are largely intact, and that any differences with RMs are minor and highly unlikely to play any role in the AIDS resistance of SIV-infected SMs." (PMID 24009514, 2013).
allergic asthma (3 papers, 2020 to 2023). A asthma with a basis in a pathological type I hypersensitivity reaction. "In vivo allergic asthma modeling was performed on WT and Irf7-/- mice, while ILC2s cells from WT and Irf7-/- mice were cultured in vitro and subsequently studied in combination with samples from asthmatic patients." (PMID 37251373, 2023). "In an allergic asthma model, IRF7 mediated the activation and function of ILC2s cells through BCL11B, increasing the expression of IL-5 and IL-13, which in turn promoted allergic respiratory inflammation and allergic asthma." (PMID 37251373, 2023).
autoimmune pancreatitis (3 papers, 2022 to 2024). "A previous study has reported that highly expressed IRF7 in the pancreas is implicated in immunoinflammatory diseases such as autoimmune pancreatitis and pancreatic ductal adenocarcinoma." (PMID 36527108, 2022).
enterovirus infection (3 papers, 2019 to 2022). "Enterovirus infection induces the cleavage or degradation of host factors, including RIG-I, MDA5, MAVS, TRIF, and IRF7/9." (PMID 35782136, 2022). "During enterovirus infection, the 3C protease induces cleavage of TIR-domain-containing adapter-inducing interferon-β (TRIF), interferon regulatory factor 7 (IRF7) and transforming growth factor-β-activated kinase 1 (TAK1) to escape host antiviral signaling." (PMID 31036013, 2019).
fibrosis (3 papers, 2016 to 2024). the formation of excess fibrous connective tissue in an organ or tissue in a reparative or reactive process. "Using the AngII infusion model to induce non-ischemic cardiac fibrosis, it was shown that WWP2 stabilized interferon regulatory factor 7 (IRF7) by non-degradable mono-ubiquitination, a process leading to induced expression of the chemokine CCL5." (PMID 39595580, 2024).
Hepatic steatosis (3 papers, 2017 to 2025). Steatosis is a term used to denote lipid accumulation within hepatocytes. "Similar to our findings, IRF7 knockout improved glucose homeostasis and insulin sensitivity and ameliorated diet-induced hepatic steatosis." (PMID 29254175, 2017). "Mechanistically, MCT4 alleviated hepatic steatosis by regulating a group of hub genes such as Arg2, Olr1, Cd74, Mmp8, Irf7, Spp1, and Apoe, which in turn impacted multiple pathways involved in lipid metabolism and inflammatory response, such as PPAR, HIF-1, TNF, IL-17, PI3K-AKT, Wnt, and JAK-STAT." (PMID 40330148, 2025). "Moreover, IRF7, the principal regulator of IFN, increased triglyceride, cholesterol, free fatty acid, and induced lipid accumulation in HFD-fed mice, while knockdown of IRF7 ameliorated diet-induced hepatic steatosis and improved glucose and lipid homeostasis." (PMID 33924165, 2021).
lung disease (3 papers, 2020 to 2024). "For instance, STING-associated lung disease due to a gain of function mutation in the protein (N153S) is T cell dependent but does not require IRF3/IRF7 or IFNAR." (PMID 33488589, 2020).
lymphoma (3 papers, 2010 to 2023). A malignant (clonal) proliferation of B- lymphocytes or T- lymphocytes which involves the lymph nodes, bone marrow and/or extranodal sites. "Indeed, IRF7 expression was frequently detected in LMP1-positive primary lymphomas of the human central nervous system, and the association between LMP1 and IRF7 expression was statistically significant." (PMID 23793113, 2013).
osteosarcoma (3 papers, 2022 to 2024). A usually aggressive malignant bone-forming mesenchymal neoplasm, predominantly affecting adolescents and young adults. "Moreover, loss-of-function and gain-of-function studies have proved the critical functions of IRF7 in suppressing aerobic glycolysis of osteosarcoma cells as evidenced by glucose uptake, lactate production, extracellular acidification rate, and oxygen consumption rate." (PMID 34975316, 2022). "In oncological contexts, IRF7 acts as an inhibitor of pyruvate kinase M2 (PKM2) transcription, consequently downregulating the Warburg effect and influencing the malignancy of osteosarcoma." (PMID 38671352, 2024).
pancreatic cancer (3 papers, 2021 to 2024). "In pancreatic cancer patients, the expression of IRF7 was significantly associated with the pathology stage." (PMID 39457004, 2024). "The research utilises single‐cell RNA sequencing and spatial transcriptomics to identify the mechanisms by which IRF7 in M1 macrophages inhibits the occurrence of pancreatic cancer by regulating lipid metabolism‐related pathways." (PMID 39118300, 2024). "This document is a detailed study on the role of IRF7 and RPS18 in regulating pancreatic cancer progression, specifically through the interactions between M1 macrophages and pancreatic cancer cells." (PMID 39118300, 2024).
parasitic infections (3 papers, 2020 to 2024). "Given its multifunctional transcription factor activity, IRF7 also has an important role in host defense against parasitic infections." (PMID 37251373, 2023). "However, IRF7 significantly impaired early splenic Th1 responses and limited control of parasitemia during PbA infection." (PMID 39702382, 2024). "Irf7−/− mice only partially recapitulated the decreased brain pathology and protection from P. berghei (ANKA) lethality observed in Ifnar1−/− mice, but loss of IRF7 perfectly phenocopied the decreased parasitemia observed in Ifnar1−/− mice." (PMID 33408718, 2020). "Therefore, the role of IRF7 in parasitic infections remains to be characterized." (PMID 37251373, 2023). "First, a group showed that Ifnar1−/− and Irf7−/− mice better controlled parasitemia in non-lethal P. chabaudi infection compared to WT controls." (PMID 33408718, 2020).
respiratory infection (3 papers, 2020 to 2023). "We found an increase in ASM area and proliferation in IRF7-/- compared to WT infected mice, suggesting that ASM alterations are initiated in response to a severe respiratory infection in early-life." (PMID 32658914, 2020).